LIN28A (lin-28 RNA binding posttranscriptional regulator A)
Diseases named in the same sentence as LIN28A in open-access papers (continued):
Sharing a sentence is not in itself a finding about the gene and the disease.
tumor (continued). "Therefore, the co-expression of SALL4 and LIN28A in AME observed in this study may play a significant role in tumour pathogenesis." (PMID 37559082, 2023). "In conclusion, LIN28A and its paralog LIN28B are RBPs closely associated with tumors, and they exert their biological function by inhibiting the biosynthesis of members of the tumor suppressor gene let-7 miRNA family or changing the translation efficiency of the mRNA they bind." (PMID 36831493, 2023). "Thus, LIN28A is a marker for tumor cell invasiveness as well as a potential therapeutic target." (PMID 28587210, 2017). "For instance, Lin28 A/B, an RBP that is up-regulated in multiple cancer types, regulates miRNA processing and affects the maturation of let-7a, thereby promoting tumor growth and metastasis." (PMID 40271197, 2025). "Tumor cells in mETMR-FBO (NES+, some expressing nuclear β-Catenin) and hETMR-FBO (NES+; LIN28a+) recapitulated the major histopathological features of primary ETMR, including a similar neuronal differentiation profile." (PMID 40562749, 2025). "Two sets of genes were chosen, PDGFRA, Lin28A, THBS1, JUN, PLCB1 and GABRA5, which were found to be up- and down-regulated, respectively, in support of tumour cell proliferation." (PMID 38000389, 2024). "Further, replenishment led to reduced lin-28 homolog A (LIN28A) levels and concomitant increases in let-7 (MIRLET7B) tumor suppressor miRNAs, creating a sustained reversion of cell phenotype." (PMID 39522951, 2024). "In this study, LIN28A immunostaining showed nuclear and cytoplasmic localisation limited to the central cells of the AME tumour islands." (PMID 37559082, 2023). "They discovered that both LIN28A and LIN28B expression promote tumor initiation, but LIN28B-induced tumors more frequently progressed to advanced adenocarcinomas in intestinal tissues and in a genetic mouse model." (PMID 37304235, 2023). "IHC staining for SALL4, LIN28A, and KLF4 was predominantly observed in the epithelial cells of the tumour islands." (PMID 37559082, 2023). "We also demonstrated that increased expression of miR-15a-5p resulted in CXCL10 downregulation, followed by downregulation of the oncogene LIN28a and p-ERK signaling, leading to upregulation of the tumor suppressor let-7 family miRNAs." (PMID 34785791, 2022). "As anticipated, ectopic expression of LIN28 dramatically enhanced the cell migratory/invasive capabilities, while knockdown of LIN28A in tumor cells showed an opposite effect." (PMID 35102250, 2022). "Overall, our findings are consistent with miR-15a-5p’s role as a tumor suppressor that acts by downregulating CXCL10 and LIN28a expression through inhibition of the MAPK-ERK pathway." (PMID 34785791, 2022). "Among the others, cells depleted of Lin28A and SNHG14 and overexpressing IRF6 had the smallest tumor volumes." (PMID 32527996, 2020). "IHC staining indicated a lower expression level of Lin28A and ROCK2 in the tumor tissues of A2780 Ctrl group while a higher expression level of Lin28A and ROCK2 in A2780 Lin28A group." (PMID 30266988, 2019). "Next, we performed a qRT-PCR analysis on treated and untreated tumor cells revealing significant downregulating of NCAM1 expression, as well as downregulation of several self-renewal genes (e.g., LIN28A, OCT4, and KLF4) in the anti-NCAM1 treated cells." (PMID 31477684, 2019). "For example, the RNA binding protein and proto-oncogene LIN28A and TUT4 work together to polyuridylate pre-let-7, thereby blocking biogenesis and function of the tumor suppressor let-7 microRNA family." (PMID 30057901, 2018). "LIN28A and LIN28B exert their biological functions through repressing the biogenesis of the tumor suppressor let-7 microRNA family as well as modifying the translation efficiency of mRNAs that it binds." (PMID 28400788, 2017). "Paraffin-embedded tumour samples were reviewed by a single pathologist and tested for immunohistochemistry (IHC) expression of Ki-67, ERCC1, Bcl-2, and Lin28a." (PMID 28955403, 2017).
tumor (continued). "We found frequent overexpression of the cell-reprogramming factors LIN28A and LIN28B in AT/RT primary tumor samples and cell lines." (PMID 25638158, 2015). "In this study we use human primary tumor samples, GBM-derived human cell lines and human neural stem cells to investigate the role of LIN28A in malignant gliomas in vitro and in vivo." (PMID 23846349, 2013). "In gain-of-function experiments, expression of LIN28A in weakly tumorigenic GBM cell lines led to increased tumor formation and tumor size in vivo and increased GBM invasion in vitro." (PMID 23846349, 2013). "Our findings that LIN28A is expressed in GBM and can facilitate and enhance tumor formation of GBM neurosphere cell lines further support the oncogenic potential of somatic cell reprogramming factors." (PMID 23846349, 2013). "The primary known targets of LIN28A and the related protein LIN28B are the let-7 family of tumor suppressing microRNAs." (PMID 23846349, 2013). "An in vivo model with the sole overexpression of LIN28A in GFAP+ neural precursor cells does not lead to tumor formation but results in a transiently higher proliferation rate during embryonic development." (PMID 40680886, 2025). "It is also worth noting that overexpression of LIN28A neural progenitor cells in vivo is not sufficient to drive tumor formation, meaning LIN28A overexpression alone is not oncogenic." (PMID 41473749, 2025). "The aim of this study was to investigate if coactivation of LIN28A and the WNT pathway (by expression of a stabilized CTNNB1) in neural precursor cells affect brain development and are sufficient and necessary to initiate tumor formation." (PMID 40680886, 2025). "IHC showed the diffuse expression of Lin28A and focal expression of SYN and NeuN in tumor cells." (PMID 36353532, 2022). "LIN28A binds to the terminal ring of precursor let-7 (pre-let-7) and enforces terminal uridine transferase (TUTase) ZCCHC11, which can acidify pre-let-7 polyuridine, thereby blocking miRNA biogenesis and tumor suppressor function." (PMID 35954475, 2022). "The fact that LIN28A overexpression did not result in tumor formation does hence not preclude a potential role of LIN28A as a tumor-promoting factor in combination with other aberrations." (PMID 34801069, 2021). "In addition to confirm the RNA-Seq data, the study of LIN28A regulation by MEK1ca and HOXB8, together with LIN28A oncogenic activity, suggested that HOXB8 reversion of MEK1ca neoplasia at least partly relies on transcriptional downregulation of LIN28A." (PMID 34445617, 2021). "Note that the LIN28A/B expression levels were very low and did not correlate with the tumor purity (Spearman’s correlation coefficient r = 0.02 and −0.01, p = 0.7 and 0.85 for LIN28A and LIN28B, respectively)." (PMID 35008302, 2021). "In addition, 5-fluorouracil (5-FU), LIN28A, let-7, RASSF5, and ALKBH5 were shown as top 5 upstream regulators, all of which have been reported to be related to tumor formation." (PMID 30286143, 2018). "Specifically, LIN28A binds the terminal loop of precursor let-7 and recruits the Terminal Uridylyl Transferase (TUTase) ZCCHC11 that polyuridylates pre-let-7, thereby blocking microRNA biogenesis and tumor suppressor function." (PMID 28400788, 2017). "The expression of pluripotency markers, OCT3/4, NANOG, SOX2, and LIN28A, did not exhibit significant correlation with tumor formation latency and incidence, and the integration of reprogramming factor genes into genome of hiPSCs did not also affect the transcript expression." (PMID 30286143, 2018). "As LIN28AB expression is limited predominantly to tumor cells and conditional mouse knockout of either Lin28a or Lin28b at 6 weeks of age yields no overt phenotypes, it is anticipated that therapeutics targeting the LIN28/let-7 pathway will have minimal side effects in patients." (PMID 28400788, 2017).
tumor (continued). "Our results showed that Lin28A protein level is elevated with increase in tumor size, even though the difference between them is not significant, whereas the expression of Lin28B protein has not shown any difference between different tumor size stages." (PMID 27793004, 2016). "Additionally, by repressing let-7, LIN28A/B indirectly upregulates cell cycle regulators targeted by let-7 such as cyclinD1/2, CDK6, CDC34, CDC25A, and TRIM71, and cell proliferation pathway targets PI3K/AKT, MAPK, MYC, RAS and BLIMP1 leading to aberrant proliferation of tumor cells." (PMID 32365712, 2020). "Here, we showed that the lack of LIN28A and LIN28B had no impact on liver development or function, but largely abrogated tumor initiation driven by powerful oncogenes such as NRAS, CTNNB1, YAP, and AKT." (PMID 38875287, 2024). "Similar to the DEN-induced HCC progenitors, these lesions expressed IGF2BP3 and were LIN28B but not LIN28A positive, suggesting a greater importance for LIN28B in tumor initiation." (PMID 38875287, 2024). "Using immunohistochemistry, tumor cells presented a preserved expression of INI1, BRG1, and there was no immunopositivity for LIN28A or BCOR." (PMID 37349135, 2023). "We also did not observe any positive correlation between LIN28A and LIN28B and MYC at the mRNA level in TCGA dataset or by IHC between LIN28A and MYC on our 80 GBM tumor tissue microarray." (PMID 23846349, 2013). "We show here that the coactivation of LIN28A overexpression and stabilized CTNNB1 in neural precursor cells during embryonic development, defined as the GBL model, was not sufficient to drive tumor formation during the examined time frame of embryonal development." (PMID 40680886, 2025). "However, the expressions of LIN28A and LIN28B are mutually exclusive, and tumor cells expressing LIN28A do not express LIN28B, and vice versa." (PMID 36831493, 2023).
metabolic disease (6 papers, 2013 to 2024). A congenital disorder (due to inherited enzyme abnormality) or acquired (due to failure of a metabolically important organ) disorder resulting from an abnormal metabolic process. "Indeed, functional changes of additional RBPs, including but not limited to LIN28A, IGF2BP2/IMP2, and HuR, are linked to the development of metabolic diseases." (PMID 31482095, 2019).
adenocarcinoma (4 papers, 2019 to 2025). A common cancer characterized by the presence of malignant glandular cells. "Liu et al100 demonstrated that during the transition from adenocarcinoma to undifferentiated small-cell carcinoma, POU5F1, lin-28 homolog A (LIN28A), SOX2, and NANOG are sequentially activated, driving the transformation of differentiated adenocarcinoma to undifferentiated small-cell carcinoma." (PMID 40821114, 2025).
infection (3 papers, 2011 to 2017). The state of being infected such as from the introduction of a foreign agent such as serum, vaccine, antigenic substance or organism. "Lenti-miRZip-128a infection decreased the levels of mature miR-128a and significantly enhanced the expression of Lin28A, EGR2, ZFP36 and ANXA1." (PMID 28569789, 2017). "Its forced overexpression by lentiviral infection in OCI-AML3 downregulated Lin28A with ensuing repression of macrophage-oriented differentiation." (PMID 28569789, 2017).
CNS tumors (2 papers, 2013 to 2023). "Overexpression of LIN28A alone also appears to be insufficient to form CNS tumors." (PMID 37341142, 2023).
digestive system neoplasm (1 paper, 2013). A neoplasm (disease) that involves the digestive system. "It seems that Lin28B was more often expressed in the digestive system neoplasm, while Lin28A was expressed in germ cell development and gonadal tumours." (PMID 24386298, 2013).
hematopoietic cancers (1 paper, 2024). "Whereas previous studies 28,42 have focused on the oncogenic implications of Lin28B-mediated inflammation in hematopoietic cancers, our research emphasizes the broader impact of Lin28A (and probably also Lin28B) dysregulation on inflammatory processes." (PMID 39113694, 2024).
neurodevelopmental disorder (1 paper, 2021). A behavioral and cognitive disorder with onset during the developmental period that involves impaired or aberrant development of intellectual, motor, or social functions. "LIN28A is emerging as a key oncogene and biomarker for multiple cancers, and its dysregulation has also been implicated in diseases such as diabetes and neurodevelopmental disorders." (PMID 34816099, 2021).
LIN28A also shares sentences with these, for which no sentence is quoted: Impaired glucose tolerance (3 papers); melanoma (3); Obesity (3); teratoma (3); astrocytoma (2); autoimmune disease (2); colorectal (2); diabetic nephropathy (2); esophageal cancer (2); hepatic disorders (2); infertile (2); oral squamous cell carcinoma (2); ovarian tumors (2); testicular cancer (2); acute promyelocytic leukemia (1); alcoholic (1); ameloblastoma (1); anaplastic astrocytoma (1); atypical teratoid rhabdoid tumor (1); central precocious puberty (1); cholestasis (1); choriocarcinoma (1); colorectal tumors (1); demyelinating disease (1); depression (1); diabetic cardiomyopathy (1); diffuse midline glioma (1); endometrial cancer (1); endometriosis (1); esophageal adenocarcinoma (1).
A further 43 diseases each share a sentence with LIN28A in 1 paper.